SNAI2 (snail family transcriptional repressor 2)
Diseases named in the same sentence as SNAI2 in open-access papers (continued):
Sharing a sentence is not in itself a finding about the gene and the disease.
breast cancer (continued). "This in line with results reported from breast cancer, where SNAI2/SLUG expression was evaluated in different ER-positive and ER negative cell lines." (PMID 25928859, 2015). "The SNAI3 gene also appeared to be expressed in several human breast cancer cell lines, although the induction level was much lower (FC>5 in 36.3%, n = 11), while SNAI2 expression remained unchanged." (PMID 24638100, 2014). "In advanced metastatic prostate cancer, miR-203 targets BIRC5, whereas in breast cancer metastasis it targets SNAI2." (PMID 25284788, 2014). "We then investigated the role of beta-catenin in the regulation of the CA9 and SNAI2-dependent breast cancer stem cell phenotype." (PMID 24260469, 2013). "Our suggestion is supported by the fact that, in contrast to recent reports, the induction of a more mesenchymal cell phenotype increases the transcription factor mRNAs of SnaI2 and Twist1 in breast cancer cells only by a factor of 1.6 and 1.8, respectively." (PMID 23042145, 2012). "MDA-MB-231 cells are metastatic breast cancer cells that express multiple zinc finger transcriptional repressors, including Snai1, Snai2, Zeb1 and Zeb2, all of which can bind Eboxes in the E-cadherin promoter and regulate EMT." (PMID 22393397, 2012). "One study showed that Bim can be regulated by SNAI2 and inhibit tumor metastasis in breast cancer." (PMID 38773471, 2024). "Moreover, the FBXO28 inhibited SNAI2 protein level was fully rescued by treatment with a proteasome inhibitor MG132 in the Huh7 cells as well as human breast cancer MDA-MB-231, lung cancer NCI-H460 and osteosarcoma Saos-2 cell lines." (PMID 37596321, 2023). "SNAI2 also participates in regulation of the initiation and metastasis of breast cancer cells." (PMID 35768705, 2022). "RUNX2 can induce EMT and invasiveness of breast cancer cells partly by inhibiting SNAI2 expression." (PMID 35534547, 2022). "An analogous mechanism of ERα repression was reported for SNAI2 in human breast cancer." (PMID 35290621, 2022). "Interestingly, several TGF-β/Smad signaling and EMT genes, including SNAI2, were significantly upregulated in most breast cancer cells exposed to fluid forces, similar to what has already been reported in TGF-β-driven EMT in several cell lines." (PMID 34641959, 2021). "Additional patient sample staining revealed further that the cytoplasmic PEAK1 and nuclear SNAI2 expression within the stromal tissue of HER2-positive breast cancers can occur within the same fibroblastic cell types – a pattern not observed in the HER2-negative patient samples." (PMID 34239043, 2021). "In support of a cooperative role for PEAK1 and SNAI2 within the same fibroblastic stromal cells in HER2-positive breast cancers, the poor prognostic utility of PEAK1 in HER2-positive breast cancer was notably restricted to patient tumors expressing high levels of SNAI2." (PMID 34239043, 2021). "We speculate that Slug and E-cadherin may cooperate in normal mammary gland and breast cancer/stem cells and advocate for functional assessment of such Slug+/E-cadherinlow/+ (SNAI2+/CDH1low/+) “basal-like epithelial” cells." (PMID 32760736, 2020). "Importantly, the results showed that miR-203 downregulates SNAI2 levels and, unsurprisingly, miR-203 was found to be down-regulated in metastatic breast cancer cells." (PMID 31137748, 2019). "Aberrant expression of SNAI2 has been observed in many human cancers, including breast cancer." (PMID 30823890, 2019). "Leptin treatment of breast cancer cells in vitro has been shown to increase SNAI2 expression." (PMID 31118047, 2019). "In summary, these data linked EMT to SDHC suppression in breast cancer and suggested that TWIST and SNAI2, two of the master promoters of EMT, could be involved." (PMID 31164982, 2019). "Furthermore, we evaluated SNAI2 expression by immunohistochemical analysis in metastatic samples from two cohorts of patients with breast cancer treated with endocrine therapy in the advanced setting." (PMID 29921289, 2018).
breast cancer (continued). "Hence, the targeting of cIAP1 strongly reduces EGFR signaling with consequent inhibition of Snai2 expression, which is a well-known promoter of breast cancer cell aggressiveness." (PMID 29674627, 2018). "Importantly, Snai2 is more expressed in basal-like breast cancer cells, which are often characterized by increased levels of EGFR, and a correlation exists between EGFR and Snai2 expression in several cancer types, among whom breast cancer." (PMID 29674627, 2018). "Interestingly, Snai2 knockdown results in reduced invasion and metastasis formation in breast cancer models, making Snai2 an attractive target for cancer therapy even though specific inhibitors are not available yet." (PMID 29674627, 2018). "Additionally, it has been shown that SNAI1/SNAI2 can induce drug resistance in breast cancer cells via alteration of cell survival signaling pathways." (PMID 29921289, 2018). "We observed that reduction of SNAI2 expression impaired cell migration and increased E-cadherin levels in two fulvestrant-resistant breast cancer cell models, confirming a key role for SNAI2 in the control of cell motility and maintenance of a mesenchymal phenotype in resistant cells." (PMID 29921289, 2018). "Moreover, the expressions of vimentin and SNAI2 were significantly downregulated after LDR exposure in these breast cancer cells." (PMID 28240233, 2017). "To validate our findings in vivo, we tested whether high VEGFA alone or together with high SOX2, SNAI2 and decreased miR-452 expression might identify prognostic subsets of primary human breast cancers." (PMID 28504716, 2017). "In breast cancer, SNAI2 was expressed in an AP-1-dependent manner." (PMID 27323831, 2016). "In this paper, miR-203 was significantly downregulated in highly metastatic breast cancer cells, and restoration of miR-203 in highly metastatic breast cancer cells inhibited tumor cell invasion in vitro and lung metastatic colonization in vivo by repressing SNAI2." (PMID 26563372, 2016). "In contrast, RUNX2 mainly exhibits oncogenicroles in breast cancer by promoting invasiveness and metastasis via its target,SNAI2; however it may also play a tumor suppressor role in breast cancer byantagonizing ERα (thus, similar to RUNX3)." (PMID 25415051, 2014). "VIM and SNAI2 were highly expressed together with AXL in breast cancer cell lines MDA_MB_231, HS578T, and BT_549, for example, and may confer mesenchymal-like character to these lines." (PMID 22570691, 2012). "A recent study reported that stromal overexpression of the SNAIL transcription factor SNAI2 is linked to poor prognosis in patients with Luminal B HER2+ breast cancer, while the absence of SNAI2 in the stroma of Luminal B HER2+ breast tumor cells is associated with lower levels of plasma Ang232." (PMID 36008514, 2022). "In addition, USP20 can promote breast cancer metastasis by stabilizing SNAI2." (PMID 36463222, 2022). "In addition, induction of SNAI2 RNA levels by Wnt3 has been described in breast cancer cells." (PMID 33227961, 2020). "In addition, we have observed an increase in protein expression of the transcription factors SNAIL (SNAI2) and SLUG (SNAI1) in progranulin-treated breast cancer cell lines suggesting that progranulin also increase epithelial-mesenchymal transition (EMT) features of breast cancer cells." (PMID 30454027, 2018). "Our findings indicated SNAI2 as an independent prognosis biomarker in ER+ metastatic breast cancer patients treated with endocrine therapy and a potential novel therapeutic target that may contribute to reversing EMT and re-sensitizing breast cancer cells to endocrine therapy." (PMID 29921289, 2018). "In particular, the expression levels of SNAI2/Slug and vimentin (VIM), which are crucial regulators of mesenchymal transition in breast cancer, were evaluated after treatment with each inhibitor as well as their combination." (PMID 40943584, 2025).
breast cancer (continued). "Among five subtypes of human breast tumors, the expression levels of TWIST1 and its upregulated genes, Vim and SNAI2, are the highest, while its repressed target genes, CDH2 and ESR1, are the lowest in ER−/HER2− breast cancers." (PMID 38893094, 2024). "According to the hierarchical clustering analysis of 52 breast cancer cell lines, SOD2 and GPX8 genes were part of the mesenchymal gene signature and co-clustered with ZEB1, VIM, and SNAI2." (PMID 38172210, 2024). "Recently, it has been reported that TRPC1 overexpression increases markers for an EMT-like phenotype, such as zinc finger proteins, SNAI1 (SNAIL) and SNAI2 (SLUG), and VIMENTIN, by increasing invasiveness in mouse breast cancer cell lines in vitro." (PMID 37892239, 2023). "SLUG (SNAI2), one of the key EMT markers that is a member of the SNAIL zinc-finger family, is more highly expressed in breast cancer cells than in normal mammary cells." (PMID 37553661, 2023). "It has been reported that BHLHE40 can promote SNAI1 and SNAI2 expression and inhibit the expression of CLDN1, CLDN4, and CDH2 in breast cancer, promoting the migration and invasion of tumor cells." (PMID 37377917, 2023). "In the TCGA dataset, we assessed the expression of key epithelial marker E-cadherin (CDH1) and mesenchymal markers, including vimentin (VIM), MMP9, SNAI2, ZEB1, and ZEB2, about VISTA expression in breast cancer patients using Spearman correlation analysis." (PMID 37152039, 2023). "In studies on human breast cancer, expression of SLUG, an SNAI family member also known as SNAI2, increased in breast cancers compared to normal mammary epithelium; and SLUG expression had a strong correlation with the loss of E-cadherin during EMT." (PMID 37553661, 2023). "Significant downregulation of the miR-200 family, which consists of miR-141, miR-200a, miR-200b, miR-200c, and miR-429, regulates the expressions of mesenchymal markers ZEB1, ZEB2, TWIST1, TWIST2, Snai1, and Snai2 and promotes EMT in breast cancer." (PMID 37533517, 2022). "In breast cancer cells, activation of canonical Wnt signaling stabilizes the EMT transcriptional factor snail family transcriptional repressor 2 (SNAI2) by inhibiting GSK3β activity and promoting transcription of EMT-related genes." (PMID 35204808, 2022). "At the same time, we also further analyzed the expression levels of SNAI2 and SNAI3 in breast cancer." (PMID 35898399, 2022). "In MCF-7 and MCF10AT1 breast cancer cells, leptin downregulates CDH1 expression and upregulates SNAI2 expression through an autocrine mechanism that involves the expression and secretion of TGFB1." (PMID 33334030, 2020). "We thus examined the relationship between the mRNA expression levels of TGFB1 (TGFβ), CTNNB1 (β-catenin), SNAI1, SNAI2 and ZEB1 and those of Sipa1 in TCGA breast cancer patient samples." (PMID 32193333, 2020). "Mutual exclusivity data from the n = 1,105 breast cancer TCGA dataset revealed that PAPP-A has a significant tendency towards co-occurrence with mesenchymal markers Vimentin (VIM), SNAI1 (Snail), SNAI2 (Slug), Zeb1, Zeb2 and Twist1." (PMID 32792532, 2020). "Similarly, KDM6B has also been associated with the direct activation of the EMT-TF gene SNAI1, or SNAI2, in different cancer models (breast cancer cells, hepatocarcinoma cells, and CRCCs) but KDM6B might also be recruited on specific promoters involved in downstream EMT signaling." (PMID 33291363, 2020). "The NFKB pathway regulates ZEB1 or SNAI2 expression in mammary epithelial cells, and is essential for EMT and metastasis in a model of breast cancer progression." (PMID 30782064, 2019). "miR-1271 suppresses breast cancer progression and EMT phenotype both in vitro and in vivo by targeting SNAI2." (PMID 30823890, 2019). "Thus, we investigated whether SNAI2 could affect the miR-1271 expression in breast cancer cells." (PMID 30823890, 2019).
breast cancer (continued). "In breast cancer cell lines, authors showed that the expression of CD151, VIM, and SNAI2 were suppressed, while CDH1 (an epithelial marker) was upregulated by miR-506." (PMID 28405738, 2017). "Phenformin also dose-dependently upregulated mRNA levels of CDH1 with concomitant downregulation of VIM, SNAI1, and SNAI2, indicating that phenformin hinders EMT at the transcriptional level in breast cancer cells." (PMID 28947975, 2017). "Analysis of the transcriptome of the 51 breast cancer cell lines showed an inverse relationship between expression of FUT1/3 and of SNAI2 and ZEB1/2." (PMID 26908442, 2016). "The ectopic expression of miR-33b downregulated the expression of ADAM9, HMGA2, LDHA, SALL4, SNAI2 and Twist1 by more than 30% but had minimal effects on HIF-1α, RAC1, Yes1 and ZEB1 in these two breast cancer cell lines." (PMID 25919570, 2015). "Third, SNAI2/SLUG is significantly inversely correlated with ESR1 expression and prognostic in analogy to breast cancer." (PMID 25928859, 2015). "On the other hand, the down-modulated genes codify for proteins involved in cell migration and invasion (SNAI2 and B2M) as well as for proteins (TFPI2) with a tumor suppressor role in breast cancer." (PMID 24962430, 2014). "In this study, we observed that miR-506 played a role as a master suppressor of EMT in breast cancer through the direct targeting CD151, VIM and SNAI2." (PMID 23717581, 2013). "We then observed that in MCF7 cells, as well as in T-MS, hypoxia increased the mRNA expression of two crucial breast cancer stem cell regulatory genes, namely carbonic anhydrase 9 (CA9) and SNAI2, via de novo mRNA production." (PMID 24260469, 2013). "We therefore analyzed the expression of mesenchymal markers connected with EMT activation (VIM, TWIST1, SNAI1 and SNAI2) in PT, CTCs-EBF and LNM of breast cancer patients." (PMID 24217115, 2013). "Here we analyzed the role of beta-catenin in the mRNAs production and stabilization of two important breast cancer stem cell regulatory genes, i.e. carbonic anhydrase 9 (CA9) and SNAI2." (PMID 24260469, 2013). "As expected and previously reported for breast cancer-derived tumor cells, LEF1 depletion resulted in decreased steady state SNAI2 protein as well as mRNA levels." (PMID 23677615, 2013). "miR-506 suppressed the expression of mesenchymal genes such as Vimentin, Snai2, and CD151 in MDA-MB-231 human breast cancer cell line." (PMID 23717581, 2013). "The SNAI2 and SNAI1 genes have recently been identified as direct transcriptional targets of ATF3 in human mammary cells, and the murine homologs, Snai2 and Snai1 are up-regulated in ATF3-induced mammary tumors." (PMID 21304988, 2011). "We previously reported that TWIST1 induces the transcriptional activation of mesenchymal genes such as VIM (Vimentin) and SNAI2 (Snail 2) but induces the transcriptional repression of epithelial genes such as CDH1 (E-cadherin) and ESR1 (ERα) in breast cancer cells." (PMID 38893094, 2024). "In other findings, knockdown of EGR1 using EGR1 siRNA enhanced the growth and chemosensitivity of breast cancer cell lines to capsaicin.It is now reported that EGR1 can promote pancreatic cancer migration and invasion by controlling the expression of SNAI2 and modulating the EMT pathway." (PMID 38408959, 2024). "A study conducted on human breast cancer found that when SNAI2 (SLUG) and SNAI1 (SNAIL) are transfected into MCF10A cells, human breast cancer epithelial cells lose their epithelial-type shape and acquire mesenchymal-related characteristics, and this was linked to AXL increase." (PMID 38391974, 2024). "SNAI2 plays a crucial role in regulating T-cell lineages and cancer cell stemness, as well as modulating lapatinib resistance in HER2-positive breast cancer and enhancing 5-fluorouracil sensitivity in colorectal cancer." (PMID 37138850, 2023).
breast cancer (continued). "Additionally, it has been found that in rat mammary tumors, HDT treatment reduced the expression of the EMT transcription factor (EMT-TF) Snail family transcriptional repressor 1 (SNAI1) and Snail family transcriptional repressor 2 (SNAI2)." (PMID 37998036, 2023). "SLUG (or SNAI2) and SOX9 are two key TFs that regulate stemness in mammary cells, and they promote the tumorigenic and metastasis-seeding abilities of human breast cancer cells." (PMID 37117180, 2023). "Besides PSN1 cells, there was a universal increase of SNAI2 mRNA expression across other PDAC, NSCLC and breast cancer cell lines in response to 72 h Talazoparib treatment." (PMID 35864202, 2022). "In breast cancer, SNAI1 and SNAI2 expression was high, whereas SNAI3 expression was low." (PMID 35898399, 2022). "Notably, we also demonstrate that HER2-positive breast cancers contain fibroblastic stromal cells positive for both cytoplasmic PEAK1 and nuclear SNAI2." (PMID 34239043, 2021). "Having demonstrated the involvement of SNAI1, further studies must be carried out to dissect whether other EMT-TFs, such as SNAI2, ZEB1, or TWIST, are also involved in the regulation of the CMTM members in breast cancer cells." (PMID 33803139, 2021). "SNAI2 is a well-established EMT transcription factor that appears to be a key target for RUNX transcription factor complexes and is perhaps one of several genes that contribute to the metastatic nature of breast cancer cells." (PMID 32005976, 2020). "In breast cancer cells, ELF5 transcriptionally represses SNAI2 expression." (PMID 33158935, 2020). "miR-1271 suppresses breast cancer progression and EMT phenotype by targeting SNAI2." (PMID 30823890, 2019). "Interestingly, we also demonstrated that SNAI2 is a direct target of miR-1271 and miR-1271 suppresses breast cancer progression and EMT phenotype by targeting SNAI2." (PMID 30823890, 2019). "In cancer cells, Snai2 promotes aggressiveness and resistance to therapy by favoring cancer cell stem-like and EMT properties, especially in breast cancer, and it supports metastasis formation by increasing plasticity, cell motility and resistance to detachment-induced cell death." (PMID 29674627, 2018). "In contrast, growth of SNAI2-low breast cancer cells was significantly inhibited by fulvestrant alone, and downregulation of SNAI2 had no additional effect on decreasing the growth of these cells compared to standard endocrine therapy." (PMID 29921289, 2018). "To evaluate the role of SNAI2 in the control of EMT characteristics and resistance to fulvestrant, we performed gene knockdown studies with specific siRNA targeting SNAI2 in the two fulvestrant-resistant breast cancer cell models." (PMID 29921289, 2018). "In particular, in breast cancer the transcription factor Forkhead box protein M1 (FoxM1) is known to induce EMT via SNAI2 (SLUG) promoter stimulation, while in pancreatic cancer, FoxM1 upregulates ZEB1, ZEB2, SNAI2 and vimentin." (PMID 28792442, 2017). "Several findings of this study indicate that SNAI2/SLUG is an estradiol- responsive gene and ERα may play an important role in EMT in breast cancer." (PMID 25928859, 2015). "We found a strong increase in the expression of SNAI2 (∼73-fold) and SOX9 (∼67-fold) which may both contribute to the maintenance of human breast cancer stem cell phenotype." (PMID 24498388, 2014). "Microarray analysis comparing the populations in which the reporter construct is active versus inactive showed that positive cells expressed higher mRNA levels of cytokines (IL-8, IL-6, TNF) and genes (such as ATF3, SNAI2, and KLF6) previously related with the CSC phenotype in breast cancer." (PMID 25414831, 2014).